CCL3 (C-C motif chemokine ligand 3)
Diseases named in the same sentence as CCL3 in open-access papers (continued):
Sharing a sentence is not in itself a finding about the gene and the disease.
COVID-19 (continued). "To explore whether the leucocyte response is limited by COVID-19, we stimulated cells with LPS or PMA/Ion, and a clear proinflammatory response with cytokines such as TNF-α, CCL3, CCL4, IL-17a, CCL23 and CXCL8 was detected in the supernatant, indicating that leucocytes are not anergic." (PMID 35901034, 2022). "Compared to the healthy controls, patients with COVID-19 had significantly higher circulating concentrations of 19 inflammatory mediators, namely interleukins 1α, 2, 6, 7, 8, 10 and 15, CRP, SAA, ICAM-1, VCAM-1, CXCL10, CCL3, CCL26, IFN-γ, TNF-α, bFGF, PlGF and Flt-1 (P < 0.05)." (PMID 35958594, 2022). "Indeed, the bronchoalveolar fluid (BALF) of severe COVID-19 patients contains high concentrations of CCL2, CCL3, CCL4, and CCL7, and a decreased proportion of tissue-resident alveolar macrophages, but high amounts of inflammatory monocyte-derived macrophages (Liao and others 2020)." (PMID 35647937, 2022). "Analysis of plasma from patients with COVID-19 has revealed increases in cytokines, including IL-1β, IL-2, IL-6, IL-7, IL-10, TNFα, monocyte chemoattractant protein (MCP1/CCL2), granulocyte colony stimulating factor (G-CSF), and macrophage inflammatory protein 1α (MIP1α/CCL3)." (PMID 34251989, 2021). "The cytokine storm landscape of COVID-19 patients was further demonstrated in a retrospective study showing higher concentrations of IL-2, IL-7, IL-10, G-CSF, C-X-C motif chemokine ligand (CXCL)-10, C-C motif chemokine ligand (CCL)-2, CCL-3, and TNF-α in the plasma of severe COVID-19 patients." (PMID 33584335, 2020). "Chemokines such as CCL4L2, CCL3, and CCL4 and their respective receptors were also found to be enriched in severe-stage monocytes, indicating the potential of targeting these cytokines and/or their receptors with drugs for treating severe-stage COVID-19 patients." (PMID 32764665, 2020). "The altered gut microbiota due to COVID-19 may flare up the early induced ‘Cytokine Storm’ elevating the levels of IL-1β, IL-6, tumour necrosis factor-α (TNF-α), monocyte chemoattractant protein-1 (MCP-1), and macrophage inflammatory protein-1α (MIP-1α) and Chemokine C–C motif ligand 3 (CCL3)." (PMID 39294611, 2024). "Similar to IL-6, IL-10, and TNF- α, CCL-3 and CXCL-13 levels were not significantly different between mild-to-moderate COVID-19 patients, recovered individuals, and healthy controls." (PMID 38646483, 2024). "Monocytes of HD + COVID-19 patients secreted significant higher levels of the pro-inflammatory cytokines GM-CSF, IL-1β, IL8, IL-10, CCL2 and CCL3 compared to non-infected HD patients." (PMID 36675231, 2023). "We also did not detect an increase in CCL3 and CCL4 antibodies in COVID-19 convalescents compared with healthy controls in the Lugano cohort at month 6, although the amount of corresponding chemokines was elevated in their plasma." (PMID 36879067, 2023). "High levels of CCL3 and IL1B mRNA were observed in the SEV and MOD groups compared to the CTRL, indicating that these mediators of COVID-19 inflammation are not sufficiently responsive to glucocorticoid treatment." (PMID 36993968, 2023). "For example, the concentrations of MIP-1α/CCL3, soluble CD163 (sCD163), and M-CSF were elevated in all COVID-19 patients compared with HVs, regardless of severity." (PMID 33232303, 2021). "Moreover, no changes in serum levels of both CCL3 and MPO were detected; neither between groups of COVID-19 patients and HCs nor between the patient groups." (PMID 37283736, 2023). "One of the first studies to evaluate the serum cytokine storm in COVID-19 patients showed that several pro-inflammatory mediator levels, such as TNFα, IL-2, IL-7, IL-10, G-CSF, CXCL10, CCL2 and CCL3, were increased in ICU (n = 13) compared to non-ICU COVID-19 patients (n = 28)." (PMID 36941580, 2023).
COVID-19 (continued). "Concentrations of select chemokines (CXCL8, CXCL10, CCL2, CCL3, CCR1) and complement factors (C2, C9, CFD, C4BPA, C5AR1, CR1) were examined at mRNA and protein levels with regard to a COVID-19 course (ICU vs. non-ICU group) and CMV status at different time intervals." (PMID 36232655, 2022). "Critically ill COVID-19 patients exhibited an increased ratio of white blood cells/lymphocytes and higher plasma levels of C-reactive protein (CRP), IL-2, IL-7, IL-10, GSCF, IP10 (CXCL10), MCP-1 (CCL2), MIP-1α (CCL3), and TNF-α, as compared to non-ICU patients." (PMID 32998763, 2020).
viral infection (80 papers, 2007 to 2025). "Several studies demonstrated earlier that the expression of chemokines, such as Ccl2, Ccl3, Ccl4, Ccl5, and Cxcl10, during viral infection is associated with enhanced trafficking of leukocytes into the brain." (PMID 34379515, 2021). "CCR5 plays important roles during influenza infection by contributing to a suitable immune response via CCL5 to cope with the viral infection, but also subsidizing excessive inflammation and tissue damage by mechanisms associated with increased CCL3 production." (PMID 35126379, 2021). "In mice, CCL3 recruits neutrophil granulocytes to the lung in response to IFNγ-mediated signaling in a virus infection model." (PMID 40111902, 2025). "This suggests that CCL3’s influence on DCs enhances their capacity to activate T cells, leading to a more robust and effective host response to viral infections." (PMID 39836329, 2025). "It was reported that inducing viral infection in CCL3−/− mice significantly reduced the recruitment of CD8+T cells." (PMID 38684697, 2024). "Genes down-regulated in the pro-inflammatory monocytes of ACLF patients included FOS, CCL3 and LGALS2, which are mainly associated with resistance to viral infection, promotion of apoptosis, and immunosuppression." (PMID 36626090, 2023). "In viral infections, inhibiting the expression of miR-369-3p dramatically reduces the expression of antiviral response genes, including CCL3, CCL5, CTSS, CXCL11, and IRF3." (PMID 37509488, 2023). "Upon viral infection, AMs produce high levels of cellular mediators, including IL-1β, CCL3, CCL7 and CCL2, also known as monocyte chemotactic protein 1 (MCP1), which rapidly recruits CCR2-expressing bone marrow-derived monocytes into the lung." (PMID 34367190, 2021). "Given that the epithelium influences leukocyte recruitment during viral infection through chemokine signaling, we evaluated the expression of Ccl2, Ccl3, and Ccl4 in lung homogenates from PBS-treated and RSV-infected mice." (PMID 33187989, 2021). "MIP-1α/CCL3 is another regulator of C-C chemokines that functions as a protective chemokine by protecting against viral infection in the cornea." (PMID 32477330, 2020). "As matched, uninfected BMDC cultures from each individual bat are used to calculate fold change in gene expression for each timepoint, the increase in CD80 and CCL3 transcription coincided only with viral infection." (PMID 31681302, 2019). "Previous studies have identified macrophages as key producers of CCL3 during viral infection and that CCL3 production is dependent on host interferon signaling." (PMID 29466439, 2018). "A curious observation was the inverse correlation of the expression levels of the transcripts of IL-6, TNF-α, CXCL9, CCL2 and CCL3 and the virus infection dose." (PMID 24086645, 2013). "Macrophage inflammatory protein-1α (CCL3) plays a well-known role in infectious and viral diseases; however, its contribution to atherosclerotic lesion formation and lipid metabolism has not been determined." (PMID 22359597, 2012). "Here we show that CCL3-mediated neutrophil recruitment depends directly on IFNγ signaling, both in the setting of acute virus infection and in response to heterologous CCL3 expression in the respiratory epithelium." (PMID 19298652, 2009). "Similarly, the naïve macrophages became activated in response to the viral infection and expressed essential inflammatory molecules like IL-1β, CCL3, and CCL4." (PMID 35440562, 2022). "CCL3 expression is inducible in most mature hematopoietic cells by LPS, viral infection, and TNFα." (PMID 22359597, 2012). "At least 2 recent reports have documented that memory CD8+ T cells induced in a bacterial and a viral infection indeed can produce high levels of CCL3 and that expression of this gene is enhanced in highly differentiated, long-lived memory cells that can confer immunological protection." (PMID 22241983, 2011).
viral infection (continued). "Viral infection induces a variety of proinflammatory cytokines and chemokines including IL-1b, IL-6, TNFa, CCL2, CCL3, CXCL1, CXCL2, CXCL9 and CXCL1034,35." (PMID 38750107, 2024). "Limited changes were seen in the expression of CCL-3 and CCL-5, chemokines that are often raised in viral infections and help recruit both NK cells and macrophages." (PMID 39000027, 2024). "The results showed that phillyrin treatment alleviated pneumonia induced by virus infection and significantly ameliorated the upregulation of multiple pro-inflammatory cytokines and chemokines (e.g., IL-1β, CXCL1, CCL3, CCL2, CCL5 and so on) in BALF." (PMID 37957672, 2023). "An initial connection between CC chemokines (β-chemokines) and viral infections was made with the discovery that RANTES, macrophage inflammatory proteins MIP-1α, and MIP-1β (also known as CCL5, CCL3, and CCL4) effectively suppress HIV-1." (PMID 36839838, 2023). "Real-time quantitative PCR (qRT-PCR) verified that the chemokine CCL2, CCL3, and CCL5 expression levels gradually increased with prolonged viral infection (MOI, 0.5), with the increase in CCL5 expression the most obvious." (PMID 36317881, 2022). "Chiefly amongst these, CCL3 (macrophage inflammatory protein-1α; MIP-1α), CCL4, CCL5, CXCL8, and CXCL10 are broadly expressed in the context of several (murine/human) viral infections." (PMID 34835105, 2021). "Viral infection triggers the migration of circulating monocytes to the lung guided by pro-inflammatory cytokines, such as CCL2 and CCL3, increasing the number of defending mononuclear phagocytes and enhancing inflammation." (PMID 34367190, 2021). "MIP1-α/CCL3 plays an important role in modulating the inflammatory response, particularly in viral infections, by enhancing recruitment of leukocytes (ex." (PMID 33732548, 2021). "Several chemokines were also involved in response to viral infection (CCL4, CCL11, CXCL10), bacterial infection (CCL2, CCL3, CXCL10), as well as to toxic substances insults (CCL3, CCL4)." (PMID 32295518, 2020). "MIP-1α (CCL3) is a chemo-attractant for CD8+ T cells and stimulates CD8+ effector functions in viral infection and anti-tumor activity in cancers by activating DCs and natural killer cells." (PMID 31013891, 2019). "The levels of either gene expression or cytokine proteins (IL-1α, TNFα, IL-6, CXCL10, CCL5, CCL2, CCL3, CCL4, and CCL5) in RSV-infected PMФ are comparable to the H5N3 virus infection." (PMID 28558796, 2017). "We observed increased level of inflammatory mediators (IL-1α, IL-1β, IL-6, MIP-1α (CCL3), MIP-1β (CCL4), RANTES (CCL5), MCP-1 (CCL2)) following H5N3 virus infection at 4, 8 and 20 hpi compared to cells infected with the H1N1/WSN, H5N2 and H9N2 viruses." (PMID 28558796, 2017). "Changes in the expression of CCL-3 and CCL-5, chemokines associated with acute viral infection, were non-significant and showed little difference between the two arms." (PMID 39000027, 2024). "On the other hand, HCV-associated cNK cells showed a pro-inflammatory profile, with high expression of the chemoattractants CCL3, CCL4, and XCL1, and the ligand TNFSF9 (CD137L), a costimulatory signal that can induce CD8+ T cells response against viral infection." (PMID 37063898, 2023). "CCL2, CCL3, CCL4, and CCXL10 are produced in the lung in the early phase of lung inflammation, working as a chemotactic factor for macrophages, NK cells, and T cells during viral infection." (PMID 34851149, 2022). "The release of CCL3, CCL4, and CCL5 may promote the recruitment and activation of T cells during viral infection of the brain." (PMID 34399779, 2021). "Upregulated expression of cytokines, chemokines and growth factors was commonly observed in patients and animals with lymphopenia induced by viral infection, including IL-2, IL-6, IL-12, IL-18, IL-1β, IFN-γ, CCL2/MCP-1, CXCL1, CXCL8/IL-8, CCL3/MIP-1-α, CCL7/MCP-3, CXCL10/IP-10 and CXCL9/MIG." (PMID 34578457, 2021).
viral infection (continued). "Viral infection also stimulated high levels of CCL3 and CCL5 production from microglia, but not from astrocyte cultures." (PMID 27207308, 2016). "CCL-3 and CCL-4 are known to be involved in responses to certain viral infections, but, in addition to macrophage activation, they can drive cell proliferation and may encourage viral propagation such as in Epstein-Barr B-cell infection." (PMID 25323767, 2014). "To explore the effect of SPJ treatment on cytokine expression, we used real‐time PCR and observed that viral infection led to increased expression of cytokines and chemokines, including IL‐6, IL‐1β, TNF‐α, IL‐10, IFN‐α, IFN‐β, and IFN‐γ, as well as CXCL‐2, CXCL‐10, CCL‐2, CCL‐3, and CCL‐5." (PMID 37544014, 2023). "Cytokines associated with lung injuries, such as IL-1 and TNF-α could induce the production of several chemokines, such as CCL2, CCL3, CCL5, and CXCL8, culminating in a cytokine-to-chemokine-to-cytokine signaling cascade through inflammatory response to the viral infection." (PMID 36685603, 2022). "Interestingly, viral infection also leads to reduced production of CXCL5, CCL5, CCL3, and GM-CSF, which are mainly involved in the attraction and activation of granulocytes and monocytes, suggesting that SARS-CoV-2 actively inhibits the recruitment of leukocytes early in infection." (PMID 33670363, 2021). "As a consequence, levels of pro-inflammatory cytokines and chemokines, such as IL-1β, Il-6, IL-12, CCL2 and CCL3 increased within 24 hours of CL, but not PBS treatment, prior to virus infection." (PMID 19851468, 2009). "However, we detected no further induction of IFN-α after virus infection despite a surge of pro-inflammatory responses (IL-6, IL-1β, TNF-α, IFN-γ CCL2, CCL3, and CXCL10) compared to mature hamsters." (PMID 37122119, 2023).
multiple myeloma (71 papers, 2008 to 2025). "The elevated level of CCL3 in serum is associated with a worse prognosis for patients with diffuse large B cell lymphoma, extranodal NK/T-cell lymphoma, and multiple myeloma." (PMID 33076281, 2020). "Our results demonstrated that myeloma cells secreted high levels of CCL3 in the bone marrow microenvironment and caused defective erythropoiesis of HSPCs by downregulating the expression of transcription factors in HSPCs, which resulted in anaemia." (PMID 33239656, 2020). "Myeloma cell infiltration causes elevated expression of CCL3 in BM, which suppresses the erythropoiesis of HSPCs and results in anaemia by downregulating the level of GATA1 in HSPCs." (PMID 33239656, 2020). "Experiments also implicated CCL3 in multiple myeloma, a condition characterized by pathological osteoclastogenesis." (PMID 29666038, 2018). "Targeting of the CCL3/CCR5 axis with MVC in combination with Bortezomib offers a promising therapeutic strategy against myeloma, as demonstrated by both in vitro studies and xenograft mouse models." (PMID 39953613, 2025). "Their study showed that CCL3, produced by myeloma cells, induced the release of HMGB1 by osteocytes, which in turn stimulated RANKL expression, a key driver of osteoclast activation and bone resorption." (PMID 41153795, 2025). "Elevated CCL3 expression was also observed in bone biopsies from patients with multiple myeloma, where it correlated with increased bone disease and poorer clinical outcomes." (PMID 41153795, 2025). "Myeloma-secreted CCL3 and paracrine CCR5 significantly promoted M2 macrophage polarization by activating PI3K/AKT/RhoA signaling, which in turn enhanced myeloma proliferation, inhibited apoptosis, and reduced Bortezomib sensitivity." (PMID 39953613, 2025). "CCL3 and its receptor CCR5 have been shown to reduce osteocalcin, causing osteoblast dysfunction while enhancing pathogenesis in myeloma-induced bone disease." (PMID 38684697, 2024). "In light of erythropoiesis, elevated levels of CCL3 in the serum of patients with multiple myeloma have been described to suppress the maturation of erythroblasts into reticulocytes, leading to anemia." (PMID 39231178, 2024). "Macrophage inflammatory protein-1α (MIP-1α)/Chemokine C-C ligand-3 (CCL3) is involved in pathogenesis of a few inflammatory conditions such as multiple myeloma and rheumatoid arthritis." (PMID 39195210, 2024). "Studies have shown that CCL3 contributes to the development and progression of various malignancies, such as esophageal cancer, breast cancer, osteosarcoma, leukemia, and multiple myeloma." (PMID 36691046, 2023). "CCL3 levels are elevated in the bone marrow of most patients with active myeloma and the levels of CCL3 correlate with the extent of bone disease." (PMID 35399952, 2022). "In vitro experiments have shown that high expression of CCL3 in multiple myeloma cells can promote osteoclast maturation in a RANKL-independent manner." (PMID 36468006, 2022). "Increased levels of MIP-1α (also known as CCL3), a chemokine in inflammatory diseases such as rheumatoid arthritis, and in tumors such as multiple myeloma, have been reported." (PMID 36614125, 2022). "CCL3 levels are elevated in myeloma patients and not only correlate with the extent of bone disease but are also inversely correlated to patient survival." (PMID 35399952, 2022). "The CCL3 chemokine or MIP1α, secreted by myeloma cells, triggers osteoclastogenesis by binding to chemokine receptor type 1 (CCR1) and CCR5 on OOCs." (PMID 33806209, 2021). "In our cellular interaction analysis, myeloma cells displayed an upregulation of inflammatory cytokines (e.g., CCL3, GRN, AREG, and MIF) that target receptors primarily expressed in the myeloid and dendritic cell compartment." (PMID 34845188, 2021). "Targeting CCL3 is a potential strategy against anaemia and bone disease, which means killing two birds with one stone in patients with multiple myeloma." (PMID 33239656, 2020).